ENSG00000267740 (novel protein)
Gene: Protein-coding gene on chromosome 19 (5,866,171 to 5,903,787, reverse strand). Ensembl gene ENSG00000267740.
Genetic constraint (gnomAD): Loss-of-function variants: 11 observed, 10.79 expected, observed/expected ratio (o/e) 1.02, 90% interval 0.64 to 1.65. Missense variants: 191 observed, 179.27 expected, observed/expected ratio (o/e) 1.07, 90% interval 0.95 to 1.2. Synonymous variants: 94 observed, 80.35 expected, observed/expected ratio (o/e) 1.17, 90% interval 0.99 to 1.39.